CD24 (CD24 molecule)
Diseases named in the same sentence as CD24 in open-access papers (continued):
Sharing a sentence is not in itself a finding about the gene and the disease.
breast cancer (continued). "Mice transplanted with CD24−/CD44+‐breast CSCs exhibited a significant increase in tumor size and weight as compared with that of CD24+‐breast cancer cells, suggesting the high tumorigenic potential of breast CSCs as compared to cancer cells." (PMID 38522013, 2024). "Mesenchymal-like CSC (M-CSC) subtype has been established in breast cancer: mesenchymal-like CSCs are highly invasive, and express high levels of CD44 cell surface marker but low levels of CD24 marker (CD44high/CD24low)." (PMID 39546568, 2024). "CD24 and CD44 expression on breast cancer cells have been shown to correlate with disease aggressiveness and risk of metastasis." (PMID 40051976, 2024). "Using the machine learning-based imaging analysis and the DISVT, we quantified EVs that are positive for EpCAM or CD24 and examined their ability to detect HER2-positive breast cancer at different stages." (PMID 39513819, 2024). "In clinical studies whit human breast cancer tissue obtained before and after chemotherapy found that CD44 + /CD24- or ALDH1 + tumor cells significantly increased after chemotherapy." (PMID 39180549, 2024). "Real-time PCR analysis showed that SMS2 decreased CD24 transcription level but increased the transcription levels of stemness-related genes including CD44, ALDH, OCT 4 and SOX2 in breast cancer cells (P < 0.05)." (PMID 38285090, 2024). "In the serum of breast cancer patients, the researchers were able to display discrimination in the concentration of CD24 (1.8-fold) and CD340 (1.6-fold) between healthy donors and breast cancer individuals." (PMID 38425422, 2024). "CSCs are also called TICs, because when inoculated into severe combined immunodeficiency disease (SCID) mice, represent the minority of breast cancer cells capable of forming new tumours and are CD44+/CD24–/low/lineage–4." (PMID 39003349, 2024). "Studies suggest the presence of a subpopulation of cells with stem cell-like properties within breast cancer, identified using stem cell markers CD44+/CD24-." (PMID 39239559, 2024). "In the present investigation, we analyzed the role of miR-204 in the CSCs (CD44+/CD24−) isolated from MDA-MB-231 and Hs-578t breast cancer cell lines on VM and angiogenesis." (PMID 38392969, 2024). "It was observed, in comparison to normal breast tissues, there was a significant increase in the CD24 and NDRG1 expression in breast cancer." (PMID 37842046, 2023). "Previous research also confirmed that by downregulating the CD24 and CD47 proteins on breast cancer cells using the tumor suppressor gene ZBTB28, the phagocytic activity of macrophages increased." (PMID 37875918, 2023). "Compared with CCR5− breast cancer cells, the CCR5+ cells can form more mammospheres and are enriched with EpCAM+CD44+CD24+ cells." (PMID 37759462, 2023). "Breast cancer cells express multiple types of CAM, including PSGL-1, CD24, sLex, MUC1, CD 44, MUC1, LFA-1 (integrin αLβ2), VLA-4 (integrin α4β1), and ALCAM, whereas melanoma and lung cancer have limited CAM expression." (PMID 37190188, 2023). "Anti-CD24 mAb ALB9 reduced lung metastasis in the highly metastatic bladder and breast cancers and prolonged survival." (PMID 37894750, 2023). "In breast cancer, the CD44+/CD24- stem cell population was significantly increased in cancer cells induced by radiotherapy." (PMID 37213675, 2023). "We first investigated the expression of the oncoprotein c-Myc and four breast cancer stem cell (BCSC) biomarkers: CD44, CD24, CD133 and ALDH1A1." (PMID 37353799, 2023). "In this research, we performed immunohistochemical (IHC) staining on sixty breast cancer surgical specimens for c-Myc, CD44, CD24, CD133 and ALDH1A1." (PMID 37353799, 2023). "Another anti-CD24 antibody, clone SN3, inhibited tumor growth by promoting the macrophage-based phagocytosis of ovarian and breast cancer cells and increased the phagocytosis of mantle cell lymphoma cell lines by M2-like macrophages." (PMID 37894750, 2023).
breast cancer (continued). "Further, PD-L1 knockdown in breast cancer cells downregulated the expression of CD44 and upregulated the expression of CD24, suggesting that PD-L1 expression positively regulates stem-like cells activity in the cancer tissues." (PMID 36604635, 2023). "High expression of CD44, CD133, ALDH and low expression of CD24 are well-acknowledged biomarkers in maintaining the stemness of CSC in solid tumors, including breast cancer and lung cancer." (PMID 37353799, 2023). "Particularly, the E-selectin interacts with its ligands expressed on breast cancer cells, including platelet selectin glycoprotein ligand-1 (PSGL-1), cluster of differentiation 24 (CD24), sialyl-Lewis X (sLex), and mucin-1 (MUC1) to allow rolling." (PMID 37190188, 2023). "The basal-like subtype is a triple-negative aggressive BC with a poor clinical outcome, consisting of a great proportion of breast cancer stem cells and characterized by the most common BCSC biomarkers, CD44+/CD24−/low and ALDH1+." (PMID 37374142, 2023). "For breast cancer cases, the CD44 high/CD24 low phenotype exacerbates aggressiveness, accelerates antitumor drug resistance and facilitates tumor progression." (PMID 37353799, 2023). "In breast cancer, HOXC11 couples with steroid receptor coactivator 1 to inhibit the expression of differentiation protein CD24 and apoptosis protein PRKC apoptosis WT1 regulator (PAWR) function from promoting the progression of breast cancer." (PMID 36823149, 2023). "To determine the expression status of the C1ql4 gene in breast cancer stem cells, we isolated CD44+CD24- cell populations from MCF-7 cell lines by flow cytometry." (PMID 37324011, 2023). "Our results further confirm the low expression of CD24, high expression of ALDH1A1 and stem cell self-renew genes in B7-H4-KO breast cancer cells." (PMID 37794509, 2023). "In the breast cancer model, mice were injected into the left and right fat pads with tumor implants containing CD44+CD24– and CD44+CD24+ CSCs, respectively." (PMID 36810098, 2023). "Crassolide not only significantly reduced the viability of human breast cancer cells and murine mammary carcinoma cells, but also increased ICD and decreased CD24 expression in the latter." (PMID 37103364, 2023). "CSCs have been shown to exhibit three interchangeable phenotypes in breast cancer, namely, ALDH+, CD44+CD24−, and ALDH+CD44+CD24− CSCs, which indicates the plasticity and heterogeneity of CSCs." (PMID 36890838, 2023). "In breast cancer tissue samples, MMP1, SDC1, CD24, and SPP1 showed higher protein expression compared with that in tumor-adjacent tissues, and their expression was positively correlation with tumor subtype and grade." (PMID 35037689, 2022). "Calreticulin maintains the breast CSC properties of CD24-/CD44+ and ALDH+ and promotes breast cancer progression via Wnt/β-catenin signaling in an HIF-1-dependent manner." (PMID 35464064, 2022). "Currently, the CSC surface markers CD24, CD44, CD133 and ALDH have been widely used in breast cancer for the isolation of BCSCs." (PMID 35053617, 2022). "Our results indicated that MMP1, CD24, SDC1, and SPP1 are potential novel prognostic biomarkers and candidate immunotherapy targets for breast cancer." (PMID 35037689, 2022). "Higher expression of the endothelial marker ANTXR1 was found on the cell surface of CD44+CD24− and ALDH1+ of the TMD231 breast cancer cell line." (PMID 35563449, 2022). "Based on the positive correlation between sPD-L1 level and the percentage of PD-1+CD19+CD24+CD38+ Bregs, we further investigated the function of sPD-L1 in the serum of breast cancer patients." (PMID 35935985, 2022). "To further validate our results from PyMT tumors, we also utilized a human luminal breast cancer cell line, MCF-7, and its sorted BCSCs, CD24−/CD44+ for determining BGN expression." (PMID 35053617, 2022).
breast cancer (continued). "Since then, CSCs have been reported in other cancers: breast cancer (CSC markers: CD44, CD24, and ALDH-1), colon cancer (CSC markers: CD24, CD44, CD133, and LGR5), and melanoma (CSC markers: CD34 and ABCB5)." (PMID 35740975, 2022). "It was also reported that CD24 contributes to anti-oxidant activity, and its elevated expression enhances oxidative stress in the CD44(+)/CD24(-) phenotype of breast cancer." (PMID 36497040, 2022). "The percentages of high protein expression of CD24, SDC1, and SPP1 were 28.6, 34.2, and 19.2% in breast cancer tissue, compared with 1.5, 1.5, and 1.1% in pan-cancer tissue, respectively (P=0.00, P=0.00, and P=0.00)." (PMID 35037689, 2022). "Higher MMP1, SDC1, SPP1, and CD24 expression was correlated with worse overall survival (OS) and relapse-free survival (RFS) in breast cancer patients." (PMID 35037689, 2022). "In our study, CD24 protein expression was positively correlated with tumor grade, subtype and SDC1 expression, with higher expression of CD24 in breast cancer tissues compared with tumor-adjacent tissues." (PMID 35037689, 2022). "For example, after breast cancer metastasis, in sporadic pleural effusion, breast cancer cells are rich in CSC-like cell populations with high CD44 expression and low CD24 expression." (PMID 35151264, 2022). "Apart from CD44+CD24−/low and ALDH1+, various markers have been reported to identify and isolate BCSCs in human and mouse breast cancer, which supports further research on BCSCs and provides a premise for clinical BCSC targeting." (PMID 35805056, 2022). "The expression of CD24, MMP1, SDC1, and SPP1 was much higher in breast carcinoma tissue than in Para cancerous tissues analyzed by Gene Expression Profiling Interactive Analysis (GEPIA) and ONCOMINE." (PMID 35037689, 2022). "TNBC and luminal breast cancer patients with a higher frequency of CD44-/CD24- cells had a worse DFS, compared than those with a lower frequency of CD44-/CD24- cells following standard therapies." (PMID 34318746, 2021). "As an example, ESA+/CD44+/CD24−, and ALDH1+ were detected in breast cancer stem cells (BCSCs); CD133+ in colon, glioblasoma, gastric and lung; EpCAM, CD133/EpCAM, CD90+ ESA+CD133+ CD44+CD24+ in liver; and ESA+/CD44+/CD24+ in pancreatic CSCs." (PMID 34051847, 2021). "The knock-down of DLL1 reduces the expression of CD24 and CD44, which is the biomarker of breast cancer CSCs, and down-regulates both tumor growth and lung metastasis of luminal breast cancer." (PMID 34098945, 2021). "In breast cancer, the CD44+/CD24-/low and aldehyde dehydrogenase 1 (ALDH1) + cell phenotypes are reported to be associated with stemness." (PMID 34803167, 2021). "(D) Longitudinal measurements of metastasis rates among all breast cancer patients (n = 211), patients with ≥2% CD44+/CD24- cells (n = 68) and the C1 group of patients with <2% of CD44+/CD24- and ≥19.5% CD44-/CD24- cells (n = 153)." (PMID 34318746, 2021). "The luminal breast cancer cell lines (e.g., MCF7) are reported to be enriched in the CD44−/low/CD24+ cell population." (PMID 33801148, 2021). "Using a small molecule inhibitor of IRS-1, NT157, we showed striking reduction of ER+ breast cancer tumoursphere formation and expression of stem-like markers (ALDH1, CD44/CD24)." (PMID 33144693, 2021). "Because TNBC is the most aggressive type of breast cancer, the spontaneous conversion of CD44-/CD24- TNBC cells into CD44+/CD24- CSCs was further tested in TNBC cell lines." (PMID 34318746, 2021). "CD44high/CD24−/low breast cancer cells display greater stem cell-like features and tumorigenic capacity compared to CD44− and CD24+ cells." (PMID 33649296, 2021). "In breast cancer, CD44+CD24–, ALDH+, and CD133+ are by far commonly used molecular markers to enrich and characterize breast CSC (BCSC)." (PMID 33763422, 2021).
breast cancer (continued). "Because postoperative therapies also affect the DFS, we further analyzed the frequency of CD44-/CD24- cells in TNBC patients with chemotherapy and luminal breast cancer patients with hormone therapy." (PMID 34318746, 2021). "Further, when we treated other breast cancer cell lines like MGSO-3 and MACL-1 with doxorubicin an increased expression of CD24 at cell surface was also detected." (PMID 34426608, 2021). "In the breast cancer cell lines, the conversion from non-invasive epithelial-like CD44+CD24+ cells to invasive mesenchymal CD44+CD24− progeny was also found to be activin/nodal-dependent." (PMID 34356885, 2021). "Among breast cancer circulating tumor cells, CD44+CD24+ALDH1+ subpopulation show an increased tumorigenic potential, while EpCAM+CD44+CD47+MET+ subset denotes cells with high metastatic ability." (PMID 33968778, 2021). "MYC is significantly positively correlated with breast cancer stem cell markers such as CD44, CD24, and ALDH1." (PMID 33390842, 2021). "CD24 has been routinely used in combination with CD44 for the prospective isolation of CSCs in colorectal, prostate and breast cancers." (PMID 34712602, 2021). "Here, using different breast cancer cell lines, we explored the dynamics of the CSC marker CD24 after doxorubicin treatment." (PMID 34426608, 2021). "For example, in breast cancer, cells with TPC properties can be isolated by ALDH or CD44+/CD24– markers." (PMID 34618689, 2021). "In breast cancer, in vitro stimulation with IL-6 results in an increase in the number of tumor mammospheres and CD44+/CD24+ breast CSCs." (PMID 33613850, 2021). "In breast cancer, in vitro stimulation with IL-6 increases tumor mammospheres and CD44+/CD24+ breast CSCs." (PMID 33613850, 2021). "This phenomenon was also seen in breast cancers, where tumors were found to be enriched for the CD44+/CD24– CSC subpopulation following exposure to radiation." (PMID 33681228, 2021). "Here, using different breast cancer cell lines, we have evaluated the impact of drug stress on the immediate phenotype change by tracing the CSC marker CD24." (PMID 34426608, 2021). "The breast cancer stem cell markers CD47, CD44, CD24, and CD133 have all been extensively studied and reviewed." (PMID 34205080, 2021). "First, primary human tumor cells were isolated from TNBC breast cancer patients and primary CD44+/CD24- CSCs and CD44-/CD24- tumor cells were purified by flow cytometry sorting." (PMID 34318746, 2021). "Taking adjacent tissues as a control, immunohistochemical results showed that breast cancer tissues had significantly high expression of CD44 and significantly low expression of CD24." (PMID 34789199, 2021). "In a MMTV-PyMT mammary tumor model, Lin−CD90−ALDHHi cells mark the tumor-initiating population while Lin−CD90+CD24+ cells are the high metastatic cells." (PMID 33968778, 2021). "In 2003, the existence of a highly tumorigenic sub-population of breast cancer cells displaying stem-like characteristics and identified based on CD44+/CD24- cell surface expression was first reported." (PMID 35127497, 2021). "For breast cancer, two distinct CSC populations exist and are typically defined by CD44+/CD24- cell surface marker expression or increased aldehyde dehydrogenase (ALDH) activity." (PMID 35127497, 2021). "We found that 5-mRNA prognostic signature was also significantly associated with some stemness markers in other tumors (stemness marker of breast cancer and pancreatic cancer: CD44/CD24)." (PMID 34805163, 2021). "As presented by the expression of CD44/CD24 and tumor sphere formation in MCF-7 and MDA-MB-231, CSNK1G2 also affected the expression of breast stem cell-markers only in ER+ breast cancer cells." (PMID 33861751, 2021). "These markers are expressed in a tissue-specific manner e.g., CD44, CD24 and ALDH are specific to breast cancer, CD34, CD8 to leukaemia, CD133 to colon cancer, CD44 to head neck cancer and CD90 to liver cancer." (PMID 34638469, 2021).
breast cancer (continued). "EpCAM+, CD44+, CD24- CSCs were 10-fold more likely to induce tumors compared to EpCAM-, CD44+, CD24- CSCs in breast cancer." (PMID 33889547, 2021). "miR-34a inhibits breast cancer stemness and increases the chemosensitivity to doxorubicin and paclitaxel partially by downregulating the Notch1 pathway, with reduced CD44+/CD24– BCSCs and CSC marker ALDH1." (PMID 33763422, 2021). "Breast cancer was the first human solid tumor that was shown to contain CSCs, which displayed the CD44+CD24–/lo phenotype." (PMID 33763422, 2021). "There is a relationship between CD24 and Sonic hedgehog (SHH), as knocking down CD24 in breast cancer cells have demonstrated increased proliferation, invasion, and tumorigenicity through higher expression of SHH, GLI1, and MMP2." (PMID 32426267, 2020). "In several studies, in breast cancer, CD44+CD24- mesenchymal CSCs were found at the invasive front of the tumor, while epithelial-like ALDH1+ CSCs were mostly detected in the inner regions." (PMID 32316333, 2020). "In 2003, Al-Hajj showed that tumorigenic breast cancer cells significantly exhibited stem cell-like properties, such as CD44+/CD24/low." (PMID 32986353, 2020). "Since then, the CD44+/CD24- phenotype and high ALDH activity have become the “gold standard” signature for breast cancer stem cells." (PMID 33488948, 2020). "As to molecular phenotype in breast cancer, CSCs display CD44+/CD24- phenotype and high ALDH1 activity." (PMID 32547883, 2020). "CD44+ CD24−/low ESA+ (epithelial surface antigen, also known as EpCAM) cells were identified as CSCs in a number of solid malignancies such as breast cancer." (PMID 32684928, 2020). "First, we evaluated the ALDH activity, the expression of BCSC genes (Nanog, Sox2 and Oct4), multiresistance pumps (ABCG2, ABCC1 and ABCB1) and the BCSC frequency (CD44+CD24+CD49+EPCAM+) in three human breast cancer cell lines." (PMID 33184339, 2020). "In several cancers, including breast cancer, CD44 and CD24 cell surface markers have been used to isolate CSCs; however, they should not be regarded as universal markers." (PMID 33233552, 2020). "In breast cancer, BCSCs are defined by expression of ESA, CD44 and low CD24 expression (ESA+/CD44+/CD24-), and high tumorigenic capabilities." (PMID 32673341, 2020). "Co-culture of breast cancer cells (MDA-MB-415 and MCF-7 cells) with derived primary DCs reduced levels of CD24 and HER-2, two important proteins in breast cancer proliferation and metastasis." (PMID 33322132, 2020). "We focused on the assessment of CTC heterogeneity in invasive-breast-cancer patients and the study of its stemlike features by the simultaneous usage of three markers (CD44 and CD24, ALDH1, or CD133), depending on N-cadherin expression." (PMID 32316333, 2020). "Both populations were highly tumorigenic – as few as 50 to 100 CD44+/CD24− and CD133+ breast cancer cells induced tumors in NOD/SCID mice – and expressed stem cell associated genes, including Oct4, Notch1, Aldh1, Fgfr1 and Sox1." (PMID 32430004, 2020). "In breast cancer, the combined expression of CD44 and CD24, commonly reveals enrichment of the CD44−CD24+ and CD44+CD24Lo/− cell phenotypes in luminal and basal-like breast cancer cell lines, respectively." (PMID 32545405, 2020). "Among all dopamine receptors, D1R expression is upregulated in breast cancer cells’ population that displays a stem cell phenotype (CD44+ and CD24-) compared to the differentiated breast cancer cells." (PMID 33147760, 2020). "In breast cancer, treatment with a vitamin D analog, BXL1024, reduced breast cancer stem-like cells population CD44+/CD24-/low and CD49f+/CD24-/low, identified as markers of tumor-initiating cells." (PMID 32560347, 2020). "We went on to further examine the expression of breast cancer stem cell markers CD44 and CD24, as upregulation of CD44 and downregulation of CD24 is observed in breast cancer cell line EMT." (PMID 33276802, 2020).